SIRT1 (sirtuin 1)
Diseases named in the same sentence as SIRT1 in open-access papers (continued):
Sharing a sentence is not in itself a finding about the gene and the disease.
Autoimmunity (22 papers, 2011 to 2024). The occurrence of an immune reaction against the organism's own cells or tissues. "A sensitive readout of the autoimmunity conferred by SIRT1 deficiency is the development of lymphoid infiltration of lacrimal and salivary glands." (PMID 28273169, 2017). "Currently little is understood concerning the role of SIRTs in immune responses, although it has been reported that SIRT1 deficient mice are more prone to develop autoimmunity and that Treg specific deletion of SIRT1 increases their immunosuppressive capacity." (PMID 21533107, 2011). "More severe encephalomyelitis and autoimmunity induced by myelin oligodendroglia glycoprotein (MOG) peptide is detected in Sirt1-deficient mice compared to the controls." (PMID 22069489, 2011). "Moreover, the activation of SIRT1 by naturally occurring dietary polyphenols is implicated in the regulation of oxidative stress, inflammation, and autoimmunity in response to endogenous or exogenous stimuli." (PMID 38474770, 2024). "Since the expression of these genes is necessary for eliminating self-reactive T cells, Sirt1 deficiency could increase the risk of autoimmunity." (PMID 32373350, 2020). "For example, several plant polyphenols can directly or indirectly activate SIRT1, which can reduce immune dysfunction, oxidative stress, autoimmunity, and inflammation." (PMID 39039045, 2024). "Both preclinical and clinical studies have shown that increasing the expression of SIRT1 can reduce autoimmunity as well as reduce the incidence of neurodegenerative diseases and neuroexcitation." (PMID 37892107, 2023). "SIRT1 is apparently the link between VitD3 and FOXO3a regulation, suggesting an important role of the SIRT1-FOXO3a axis in the protective activity of VitD3 in autoimmunity." (PMID 36501065, 2022). "SIRT1 promotes autoimmunity by deacetylating RORγt, the signature transcription factor of Th17 cells, and T cell–specific Sirt1 deletion or pharmacological inhibition of SIRT1 protects mice from EAE." (PMID 36136587, 2022). "SIRT1 has been found to regulate many physiological and pathological processes, such as cellular senescence and aging, apoptosis, resistance to stress, autoimmunity and regulation of metabolism." (PMID 34884952, 2021). "As an NAD-dependent deacetylase, SIRT1 has various substrates and thus plays roles in many processes, such as cell proliferation/apoptosis, stress resistance, inflammation, and even autoimmunity." (PMID 34051800, 2021). "Finally, SIRT1 has also been found to restrain B cell autoimmunity in mouse models." (PMID 34946805, 2021). "In addition, Sirt1-deficient mice had impaired T cell tolerance and were susceptible to severe experimental allergic encephalomyelitis (EAE); thus, Sirt1 activators like resveratrol were suggested as supplementary therapeutic agents for treating autoimmunity." (PMID 32373350, 2020). "As a result, a strategy to increase Treg by targeting Sirt1 has been exploited in various preclinical models of autoimmunity and inflammatory disorders and found that Sirt1 could be used as an essential target to improve Treg numbers and their suppressive activity." (PMID 32709019, 2020). "However, others have shown that SIRT1 is necessary for the production of pro-inflammatory Th17 cells through the deacetylation of transcription factor RORγt, which suggests that SIRT1 inhibitors could confer protection against autoimmunity." (PMID 31354630, 2019). "A separate study identified several acetylation sites on RORγt that became deacetylated by Sirtuin 1 (SIRT1), promoting autoimmunity." (PMID 36466897, 2022). "In addition, it would be of particular interest to selectively silence SIRT proteins in astrocytes in models of CNS pathologies since inactivation of SIRT1 and SIRT2 attenuated the pro-inflammatory phenotype of astrocytes in CNS autoimmunity and spinal cord injury, respectively." (PMID 38474102, 2024).
Autoimmunity (continued). "Notably, middle-aged patients with inflammation exhibited lower SIRT1 levels (WMD, −0.85 ng/ml; 95% CI −1.47, −0.22 ng/ml; P= 0.008; I2= 95.4%), while groups characterized by East Asian descent, plasma studies, autoimmune conditions, and musculoskeletal disorders showed higher levels." (PMID 39676853, 2024).
dementia (22 papers, 2015 to 2025). Loss of intellectual abilities interfering with an individual's social and occupational functions. "Moreover, a significant positive correlation between SIRT1 levels and dementia was found whereby dementia risk increases by a factor of 1.16 due to an increase in the SIRT1 level and a factor of 24.23 due to a decrease in the TLR4 level." (PMID 30555513, 2018). "Furthermore, miR‐543 is identified as a regulator of SIRT1 in the white matter of the brain, which possibly implicates both the miRNA and the gene in the early white matter changes in PD, and miR‐543 has also shown potential diagnostic accuracy for dementia in PD patients." (PMID 36352829, 2023). "An extended study involving PD with dementia and healthy controls illustrated that SIRT1 expression significantly differed between PD patients with dementia compared to the healthy controls." (PMID 36580159, 2023). "In a postmortem study, the levels of SIRT1 showed a slight increase in the dementia patients with Lewy bodies." (PMID 30374331, 2018). "Protein expression and activity of SIRT1 was also determined in post-mortem human brain tissue obtained from patients with PD, PD with dementia (PDD), dementia with Lewy bodies (DLB) and AD." (PMID 28578695, 2017). "SIRT1 expression was reduced in the frontal and temporal lobes of PD patients with dementia." (PMID 36580159, 2023). "However, only six of these genes emerged to be associated with AD in a certain way: HMGB1, which is related AD dementia according to ‘Disease Ontology’; KANSL1; BAZ2B; EHMT1; SIRT1; and CTBP1, which are associated with AD according to the literature data." (PMID 37175659, 2023). "Findings from this study suggest that alpha-mangostin potentially serves as a promising therapeutic compound against oxidative stress by activation of the SIRT1/3-FOXO3a pathway comparable to the effect of memantine, an anti-AD drug used for the treatment of moderate to severe dementia." (PMID 35155508, 2021). "In one of our studies, we found a significant increase in the SIRT1 level of dementia patients." (PMID 30374331, 2018). "In this study, we employ an aging model, SAMP8 mice, to explore whether BSYZ could protect dementia through SIRT1/endoplasmic reticulum (ER) stress pathway." (PMID 28521305, 2017). "We explore the potential mechanism of BSYZ on ameliorating dementia might be through SIRT1/ER stress signal." (PMID 28521305, 2017). "SIRT1 might be the key target of melatonin in the treatment of dementia." (PMID 39056330, 2024). "SIRT1 might be the critical target of melatonin in the treatment of dementia." (PMID 39056330, 2024). "The novel circadian clock gene pathways that involve autophagy, mTOR, and (SIRT1) and include FoxOs and EPO offer exciting prospects for the development of new strategies to understand cognitive loss and to overcome challenges that can limit the onset and progression of dementia." (PMID 34356626, 2021). "Notably, SIRT1 is downregulated in PD, PD with dementia, dementia with Lewy bodies and in AD." (PMID 31110473, 2019). "As a non-pharmacological treatment, YPT can improve the expression of miR-134a and SIRT-1, CREB, and BDNF proteins as much as or more than estrogen therapy, ameliorating AD-induced dementia in aged OVX rats." (PMID 39061398, 2024). "We therefore analyzed SIRT1 and SIRT2 expression in buffy coat samples from healthy subjects and patients with dementia." (PMID 35008438, 2021). "Moreover, it showed that SIRT1 is expressed in both grey and white matter, whereas in PD without dementia only changes in expression were observed in the white matter." (PMID 36352829, 2023).
endometrial cancer (22 papers, 2017 to 2025). Primary or metastatic malignant neoplasm involving the endometrium (mucous membrane that lines the endometrial cavity). "Using paraffin-embedded endometrium specimens from endometrial cancer patients and healthy control subjects, the authors examined the correlation between rs7895833, rs7069102, and rs2273773 polymorphisms of SIRT1 gene and endometrial cancer." (PMID 33435147, 2021). "Therefore, SIRT1 can suppress genomic instability, a hallmark of cancer, and potentially prevent the development of endometrial cancer." (PMID 41300302, 2025). "In the context of the association of a high-calorie diet with endometrial carcinoma, the authors supposed that SIRT1 might be downregulated in the normal endometrial glandular cells of obese women." (PMID 33435147, 2021). "In endometrial cancer cells, SIRT1 activation can facilitate DNA damage repair by interacting with Ku70, a protein involved in the DNA repair machinery." (PMID 41300302, 2025). "SIRT1 plays a role in chemoresistance, which presents a major obstacle in endometrial cancer treatment, particularly with drugs like cisplatin." (PMID 41300302, 2025). "SIRT1’s role in endometrial cancer (EC) appears to be context-dependent, with studies indicating both tumor-promoting and tumor-suppressing functions." (PMID 41300302, 2025). "SIRT1’s role in endometrial cancer can be dualistic, having both tumor-promoting and tumor-suppressive functions." (PMID 41300302, 2025). "Given its dual role in endometrial cancer, SIRT1 is considered both a therapeutic target and a biomarker for predicting chemoresistance and prognosis." (PMID 41300302, 2025). "Targeting SIRT1 with inhibitors such as EX-527 or MHY2256 has shown promise in sensitizing endometrial cancer cells to chemotherapy and overcoming chemoresistance." (PMID 41300302, 2025). "A previous study verified that SIRT1 overexpression promotes the proliferation of endometrial cancer cells in vitro and tumor formation in nude mice, and increases the resistance of endometrial cancer cells to cisplatin." (PMID 38044396, 2024). "LncRNA FIRRE facilitates autophagy and attenuates the radiosensitivity of endometrial cancer by orchestrating the miR-199b-5p/SIRT1/BECN1 axis." (PMID 39281375, 2024). "Sirtuin 1 (SIRT1) acts as a tumor promoter in endometrial cancer by targeting sterol regulatory element binding with protein 1 (SREBP1) and lipogenesis." (PMID 35181729, 2022). "The paradox is that SIRT1 can be used as the promoter of E-cadherin in endometrial cancer cells to activate its expression." (PMID 35184653, 2022). "Further studies are necessary to elucidate the actual role of SIRT1 in endometrial cancer and its correlation with ARID1A an β-Catenin." (PMID 32388637, 2020). "Up to now, the SIRT1 expression has only been described to be generally increased in endometrial cancer as well as in endothelial ovarian cancer types." (PMID 32388637, 2020). "LncRNA OGFRP1 promoted the malignant progression of endometrial carcinoma by regulating the miR124-3p/SIRT1 axis and activating the PI3K/AKT/GSK-3β pathway." (PMID 32587476, 2020).
endometrial cancer (continued). "Contrary, in progestin-resistant endometrial cancer (EC) cells, SIRT1 knockout (SIRT1-KO) results in the upregulation of progesterone receptor (PR) and FOXO1, as well as the downregulation of sterol regulatory element-binding protein-1 (SREBP-1) that increases sensitivity to progestin therapy." (PMID 34769241, 2021). "In addition, SIRT1 overexpression significantly enhanced the resistance to cisplatin and paclitaxel in endometrial carcinoma cell lines, thus using the SIRT1 inhibitor (EX527) to suppress the proliferation of these cells." (PMID 34298999, 2021). "Additionally, the authors indicated that both forced expression and activation of SIRT1 promote E-cadherin-driven reporter gene constructs, and SIRT1 is localized at the E-cadherin promoter containing E-box elements in endometrial carcinoma cell lines." (PMID 33435147, 2021). "The authors concluded that SIRT1 is involved in the acquisition of the aggressive behavior associated with endometrial carcinoma, and it can be a promising therapeutic target candidate, underlying that the EX527, as a SIRT1 inhibitor, may be a useful agent for the treatment of endometrial carcinoma." (PMID 33435147, 2021). "EMT and invasion: SIRT1 plays a role in promoting epithelial–mesenchymal transition (EMT) in both Type I and Type II endometrial cancers, though its impact is considerably more pronounced in Type II disease." (PMID 41300302, 2025). "EP300, which co-regulates target proteins along with SIRT1, has recently been reported to increase the acetylation of the RNA splicing gene DDX5 promoter, promoting the progression of endometrial cancer." (PMID 41170449, 2025). "The complex interplay between Sirtuin 1 (SIRT1) and FOXO3 in endometrial cancer (EC) remains understudied." (PMID 39266959, 2024). "On the other hand, SIRT1 suppression by EX527 dramatically decreased the tumor growth of HEC1B and HHUA endometrial cancer." (PMID 39403142, 2024). "In previous reports, OGFRP1 unregulated the expressions of LYPD3 and SIRT1 by sponging miR-124-3p in NSCLC and endometrial cancer, respectively." (PMID 33744848, 2021). "In contrast, the immunohistochemical expression of SIRT1 was significantly higher in endometrial carcinoma than in normal endometria cases regardless of BMI, and its overexpression was associated with shorter survival among patients." (PMID 33435147, 2021).
multiple sclerosis (22 papers, 2013 to 2024). A progressive autoimmune disorder affecting the central nervous system resulting in demyelination. "In this study, we investigated the possible association between SIRT1 gene polymorphisms and SIRT1 serum levels in patients with multiple sclerosis in Lithuania." (PMID 37892107, 2023). "Genetic variations in SIRT1 rs3818292, rs3758391, and rs7895833 are associated with multiple sclerosis, with possible differences in sex and age, and lower serum SIRT1 levels." (PMID 37892107, 2023). "This study has shown significant associations between the genetic variations of SIRT1 rs3818292, rs3758391, and rs7895833 and the development of multiple sclerosis, with possible differences in gender and age." (PMID 37892107, 2023). "Both T cell-specific SIRT1 deficiency and pharmacological SIRT1 inhibitor treatment inhibit Th17 differentiation and are protective in a mouse model of multiple sclerosis." (PMID 37483618, 2023). "In an animal model of multiple sclerosis, SIRT1 activation by SRT501 prevents neuronal loss and improves neuronal dysfunction." (PMID 34202956, 2021). "Here we investigated the neuroprotective potential of SIRT1 or NRF2 gene transfer using adeno-associated virus (AAV) vectors in the experimental autoimmune encephalomyelitis (EAE) model of multiple sclerosis." (PMID 29494741, 2018). "Therefore, our study investigated the role of SIRT1 level and SIRT1 (rs3818292, rs3758391, rs7895833) gene polymorphisms in patients with optic neuritis and multiple sclerosis." (PMID 36949521, 2023). "Therefore, our study aimed to investigate the role of SIRT1 levels and SIRT1 (rs3818292, rs3758391, rs7895833) gene polymorphisms in patients with optic neuritis and multiple sclerosis in the Caucasian population." (PMID 36949521, 2023). "However, further studies are needed to explore the precise mechanisms underlying the associations between genetic SIRT1 variations and multiple sclerosis and to determine the generalizability of these findings to other populations." (PMID 37892107, 2023). "Compared to stable patients with multiple sclerosis, this relapse during which p-SIRT1 protein and H3K9me3 levels showed statistically significant differences." (PMID 37483618, 2023). "A large number of cells express SIRT1 in both acute and chronic active multiple sclerosis, whereas SIRT1-mRNA and protein expressions are significantly reduced in PBMCs during relapse." (PMID 37483618, 2023). "In this study, we investigated the potential association between SIRT1 gene polymorphisms (rs3818292, rs3758391, and rs7895833) and serum levels of SIRT1 in patients with multiple sclerosis in Lithuania." (PMID 37892107, 2023). "collected PBMCs from patients with multiple sclerosis treated with gramoxone acetate to determine phosphorylated SIRT1 (p-SIRT1) and H3K9me3 levels." (PMID 37483618, 2023). "We found that serum SIRT1 levels were higher in the control group than in the multiple sclerosis group." (PMID 37892107, 2023). "In contrast to SIRT1 overexpression, SIRT1 inactivation in an established mouse model of multiple sclerosis increased the production of new oligodendrocyte progenitor cells in the adult mouse brain, improved remyelination, and delayed paralysis." (PMID 36949521, 2023). "In a mouse model of multiple sclerosis, increased oligodendrocyte generation and decreased apoptosis were consistent with increased SIRT1 expression." (PMID 36111151, 2022). "In our study, we assessed the effect of miRNAs on the expression level of neuropro-tective proteins, including neurotrophins (BDNF and NT4/5), heat shock proteins (Hsp70 and HSP27), and SIRT1 in the development of multiple sclerosis." (PMID 34202956, 2021). "We checked the expression level of genes, BDNF, NT4/5, HSP70, HSP27, and SIRT1 in PBMCs in patients with multiple sclerosis (patients with mild to moderate disability) and in the control group, healthy adults." (PMID 34202956, 2021).